GPX4 (glutathione peroxidase 4)
Diseases named in the same sentence as GPX4 in open-access papers (continued):
Sharing a sentence is not in itself a finding about the gene and the disease.
prostate carcinoma (continued). "In summary, the ferroptosis pathway factor GPX4 is highly expressed in prostate cancer and was found to correlate with the infiltration of important immune effector cells." (PMID 38705987, 2024). "Ferroptosis-mediating factors (SLC7A11, SLC3A2, GPX4) are aberrantly expressed in AR-resistant prostate cancer." (PMID 36744249, 2023). "Recent research suggests that miR-15a represses cell proliferation and facilitates ferroptosis by binding to GPX4’s 3’UTR in prostate cancer." (PMID 37065473, 2023). "Notably, scavenging ROS also led to increased levels of reduced GSH and GPX4 in prostate cancer cells treated with evodiamine." (PMID 40420092, 2025). "Additionally, a 3D matrigel drop invasion assay revealed that overexpression of GPX4 significantly reversed the inhibitory effect of evodiamine on the invasion ability of prostate cancer cells." (PMID 40420092, 2025). "Consequently, we conducted a more detailed analysis of GPX4 protein expression levels in prostate cancer cells at different time points after evodiamine stimulation." (PMID 40420092, 2025). "Therefore, the results indicated that the miR-324-3p/GPX4 axis participates in the FBI-1-mediated ferroptosis of prostate carcinoma cells." (PMID 38947389, 2024). "ROS, especially H2O2, reduce SLC7A11 and GPX4 expression in cervical cancer and prostate cancer; additionally, ROS stimulate BTB domain and CNC homolog 1 (BACH1) degradation by decreasing the expression of ubiquitin carboxyl-terminal hydrolase 47 (USP47), which can deubiquitinate BACH1." (PMID 39584140, 2024). "Additionally, another study has revealed that the upregulation of GPX4 can facilitate prostate cancer metastasis through the inhibition of ferroptosis." (PMID 38312660, 2024). "In vitro ferroptosis in prostate cancer cells has been demonstrated to be triggered by downregulation of circDUSP22; the mechanism of action is associated with the suppression of the SLC7A11/GPX4 signaling pathway." (PMID 38994627, 2024). "Moreover, transfection of prostate cancer cells with miR-15A mimics or Si-GPX4 resulted in a significant increase in intracellular Fe+ and ROS levels." (PMID 36936418, 2023). "Additionally, research investigating the mRNA profile of DU145 cells treated with sodium selenite observed an increased expression of GPX1, GPX2, and GPX4 and a decreased expression of TXNRDs in prostate cancer." (PMID 37765058, 2023). "Compared with other urinary tumors, ncRNAs in prostate cancer seems to be more inclined to affect classic genes related to ferroptosis, such as GPX4 and SLC7A11, which means that experimental design from the downstream classic gene is a good option for the study of ferroptosis-related ncRNAs." (PMID 37065473, 2023). "The two clusters showed significant differences in the expression of PRGs; CHMP2A, CHMP4C, CYCS, CASP6, CASP8, GPX4, and TIRAP have high expression levels in cluster B, suggesting that these genes may associate with poor prognosis in prostate cancer." (PMID 35813821, 2022). "In addition, we used qRT-PCR to compare the expression of hub genes (CHMP4C, GSDMB, NOD2, PLCG1, CYCS, GPX4) between prostate cancer cell lines (LNCap, PC3, DU-145) and the normal prostate epithelial cell line (RWPE-1)." (PMID 36386841, 2022). "Our study in prostate cancer in response to androgen-targeted therapies demonstrated that GPX4 dependence and ferroptosis hypersensitivity of persister cells are associated with extensive lipid remodeling, including enhanced lipid uptake and PUFA enrichment of membrane lipids." (PMID 32577235, 2020).
prostate carcinoma (continued). "Hence, GPX4 may be a potential target for inducing ferroptosis to improve the immune desert status in prostate cancer." (PMID 38705987, 2024). "Also, SNPs in MnSOD, GPX1, GPX4, CAT were found to be associated with prostate cancer." (PMID 26301412, 2015). "IHC and Western blot analyses confirmed that evodiamine induces ferroptosis in prostate cancer cells by decreasing TRIM26 expression, which in turn inhibits the stability of GPX4." (PMID 40420092, 2025). "However, the infiltration of many important immune effector cells, such as activated CD8+ T cells and gamma delta T cells, have strong correlations with GPX4 expression in prostate cancer, indicating that GPX4 may be involved in shaping the tumor immune microenvironment." (PMID 38705987, 2024). "In addition to the downregulation of GPX4 and SLC7A11, the protein level of FSP1 was also reduced in evodiamine-treated prostate cancer cells." (PMID 40420092, 2025). "Furthermore, this study reveals that SLC7A11 is highly expressed in prostate cancer; the SLC7A11/GPX4 signaling pathway regulates cellular ferroptosis, thereby influencing prostate cancer proliferation and metastasis." (PMID 41228362, 2025). "Collectively, these results suggest that evodiamine-induced ferroptosis in prostate cancer cells may not depend on regulating cellular iron metabolism, but rather on inhibiting the expression of the GPX4 protein." (PMID 40420092, 2025). "As expected, inhibition of GPX4 by RSL3 specifically induced ferroptosis, but not apoptosis, in all of the prostate cancer cell lines tested." (PMID 36928314, 2023). "Inhibitors of GPX4, such as RSL3, have exhibited inhibitory effects on treatment-resistant prostate cancer in vivo without measurable side effects." (PMID 37765058, 2023). "Therefore, we conducted WB validation for GPX4 and MBOAT2 simultaneously and found that AR indeed enhances MBOAT2 rather than GPX4 in prostate cancer." (PMID 39097593, 2024). "However, the regulation of GPX4 by HMGA2 appears more complex in prostate cancer, where the truncated HMGA2 downregulates, rather than upregulates, GPX4." (PMID 39595619, 2024).
atherosclerosis (33 papers, 2018 to 2026). A disease characterized by the build-up of fatty material and calcium deposition in the arterial wall resulting in partial or complete occlusion of the arterial lumen. "Recent evidence also indicates that E2 deficiency inhibits the NRF2/GPX4 pathway, promoting endothelial ferroptosis and accelerating vascular dysfunction and atherosclerosis." (PMID 41555389, 2026). "For example, overexpression of glutathione peroxidase 4 (GPX4) inhibited atherosclerosis progression in apolipoprotein E-deficient (ApoE-/-) mice." (PMID 39403576, 2024). "Decreased levels of Gpx4 can cause increased lipid peroxidation, resulting in ferroptosis in vascular endothelial cells, which promotes thrombosis and the development of atherosclerosis." (PMID 35186168, 2022). "As found in earlier studies, atherosclerosis in ApoE mice was associated with a decrease in the expression of GPx4 as well as changes in other markers of ferroptosis." (PMID 34579115, 2021). "In conclusion, we identified the targets of ferroptosis in atherosclerosis associated with garlic, including GPX4, DPP4 and ALOX5, providing new mechanistic insights that may be clinically relevant for combination therapies of garlic." (PMID 39108744, 2024). "Considering that reduced GPX4 expression and/or activation and increased lipid peroxidation are the main features of ferroptosis, recent studies have explored the potential association between ferroptosis and atherosclerosis." (PMID 36078133, 2022). "GPX4 has been shown to be associated with cardiovascular diseases, whereby overexpression of GPX4 in apolipoprotein E-deficient mice and in a myocardial ischemia/reperfusion mouse model inhibits the development of atherosclerosis and protects cardiac contractile function, respectively." (PMID 34327240, 2021). "Therefore, further investigations into the function of GPX4 in atherosclerosis may facilitate the development of novel diagnostic and therapeutic approaches, as well as drug development targets for the prevention and prognosis of related cardiovascular diseases." (PMID 42110150, 2026). "This review summarizes the structure and function of GPX4 and the role of this enzyme in iron toxicity and atherosclerosis." (PMID 42110150, 2026). "Treatment with E2 or ferroptosis inhibitor ferrostatin-1 alleviated atherosclerosis, lipid peroxidation, and iron deposition and upregulated the cystine/glutamate antiporter (xCT) and glutathione peroxidase 4 (GPX4) in ECs." (PMID 40507889, 2025). "Collectively, these findings confirm that catechin prevents ox-LDL-induced ferroptosis in VSMCs by activating the Nrf2/SLC7A11/GPX4 pathway, highlighting its potential therapeutic value for atherosclerosis." (PMID 40529424, 2025). "Increased expression of GPX4 was able to inhibit the development of atherosclerosis by decreasing lipid peroxidation and inhibiting the sensitivity of vascular cells to oxidized lipids." (PMID 38743322, 2025). "In vivo studies have shown that GPX4 over-expression inhibits the development of atherosclerosis by reducing the expression of endothelial cell adhesion molecules and up-regulation of endothelial necrosis and apoptosis." (PMID 39595632, 2024). "The results provide evidence that GPX4 inhibits the development of atherosclerosis by decreasing lipid peroxidation and decreasing the sensitivity of vascular cells to oxidized lipids." (PMID 36980208, 2023). "Overexpression of GPX4 significantly reduces lipoperoxide and atherosclerosis progression in ApoE(−/−) mice." (PMID 37791060, 2023). "Early studies showed that selenium supplementation, a co-factor for GPx4 activity, can stop the development of atherosclerosis plaques and reduce lesions in animal models." (PMID 36985608, 2023). "They found that GPX4 mitigates the evolution of atherosclerosis via curtailing lipid peroxidation and diminishing the sensitivity of vascular cells to oxidized lipids." (PMID 37840106, 2023).
atherosclerosis (continued). "It has been previously realized that GPX4 and lipid peroxidation play significant roles in atherosclerosis." (PMID 36078133, 2022). "GPX4 knockout can promote lipid peroxidation, leading to highly cytotoxic oxidation products for the cell and aggravating the atherosclerosis effect." (PMID 36620630, 2022). "In ApoE−/− mice, transgenic overexpression of human GPX4 delays the development of atherosclerosis by reducing lipid peroxidation." (PMID 36192693, 2022). "ACSL4 is up-regulated, while GPX4 is down-regulated in the coronary arteries of atherosclerosis patients." (PMID 36620630, 2022). "For instance, GPX1 is a potential antioxidant enzyme with a significant role in the detoxification of lipid hydroperoxides and H2O2, while GPX4 reduces oxidative stress and thus, inhibits atherosclerosis." (PMID 34419016, 2021). "GPx4 also mediates the development of atherosclerosis by regulating the oxidation of cellular lipids." (PMID 34579115, 2021). "Consistent with the findings of the present study, Fer-1 also increased GPX4 expression in mice with high-fat diet-induced atherosclerosis." (PMID 34787054, 2021). "GPx4, a ferroptosis-resistant enzyme, plays a major role in the development of atherosclerosis." (PMID 36985608, 2023). "Qing-Xin-Jie-Yu Granule (QXJYG), a traditional Chinese medicinal compound constituted of quintuple Chinese medicinal constituents, could inhibit ferroptosis through the regulation of the GPX4/xCT pathway for atherosclerosis." (PMID 37840106, 2023). "Furthermore, Fer-1 showed antioxidant effects in cell models of Huntington’s disease, kidney dysfunction, atherosclerosis, and lung cancer by reducing oxidation of lipids and ROS production, and it indirectly promoted the expression of GPx4." (PMID 36985608, 2023). "Notably, statins, the lipid-lowering drugs commonly used in atherosclerosis, can inhibit GPX4, a type of selenoprotein, leading to plaque progression." (PMID 37791060, 2023). "In addition, ferroptosis has also been linked to atherosclerosis in human coronary artery specimens by analyzing the correlation to ferroptosis markers such as PTGS2 (upregulated), ACSL4 (upregulated), and GPX4 (downregulated)." (PMID 36078133, 2022). "Consistently, GPX4 overexpression in ApoE−/− mice was shown to protect against atherosclerosis." (PMID 36192693, 2022). "Compared to wildtype mice, ApoE mice on a normal chow diet have increased aortic expression of many antioxidant enzymes, including GPx1, GPx3, GPx4 and Txnrd prior to the development of atherosclerosis, but during lesion development, the expression of these antioxidant enzymes declines." (PMID 34579115, 2021). "Simultaneously, the GPX4 rs713041T and SEPP1 rs3877899A alleles are preventing factors for the development of AAA, which confirms the substantial differences in genetic predisposition to atherosclerosis and aneurysm." (PMID 30188935, 2018). "Thus, it can be concluded that capsiate may mitigate atherosclerosis by modulating ferroptosis through the Nrf2/GPX4/SLC7A11 pathway." (PMID 40029381, 2025). "Thus, whether and how KLF11 regulates GPX4 transcription and lipid peroxidation in ECs, probably affecting atherosclerosis under diabetic conditions, is a noteworthy possibility to explore." (PMID 39462409, 2024). "As an intracellular antioxidant enzyme, glutathione peroxidase 4 (GPX4) can suppress lipid hydroperoxides, decrease EC damage from oxidized lipids, and inhibit atherosclerosis development." (PMID 39462409, 2024). "In conclusion, our findings suggest that radiation-induced endothelial ferroptosis accelerates atherosclerosis, and DDHD2 is a potential regulatory protein in radiation-induced endothelial ferroptosis through the Nrf2/GPX4 pathway." (PMID 39062593, 2024). "For instance, in an investigation of atherosclerosis induced by HUA, exposure to sUA significantly heightened macrophage iron death through the NRF2/SLC7A11/Glutathione peroxidase 4 (GPX4) signaling pathway." (PMID 38053999, 2023).
atherosclerosis (continued). "During the late stage of atherosclerosis, the levels of the iron ferroptosis-related proteins PTGS2 and ACSL4 are increased, while GPX4 expression is decreased." (PMID 37181809, 2023). "By increasing the generation of GPX4, GSH, and NADPH, and preserving cellular iron homeostasis, the NRF2-Keap1 pathway decreases atherosclerosis-related ferroptosis." (PMID 36290297, 2022). "In addition, the same interaction between the GPX4 and SELENOS SNPs was observed in the analysis that compares the frequency of genotypes between AIOD and AAA, which confirmed the substantial differences in genetic predisposition to atherosclerosis and aneurysm." (PMID 30188935, 2018). "The protective effects of capsiate against atherosclerosis may be mediated through the PI3K/AKT/NF-κB and Nrf2/GPX4/SLC7A11 signaling pathways." (PMID 40029381, 2025). "Furthermore, the severity of atherosclerosis was positively correlated with the expression of Ptgs2 and ACSL4 and negatively correlated with the expression of GPX4." (PMID 36192693, 2022).
ischemic stroke (32 papers, 2020 to 2026). A stroke disorder caused by obstruction of blood flow to the brain, due to thrombotic (local blood clot formation) or embolic (due to a blood clot or other material traveling from another site) event. "One of the creative findings in the current study is that ischemic stroke‐mediated iron overload causes the opposite alterations in endogenous antioxidant defense systems, Nrf‐2‐mediated GPX4 and SLC7A11 expression in neurons and astrocytes." (PMID 41195589, 2026). "Consistently, loss of GPX4 leads to ferroptosis, which manifests mainly as progressive cognitive dysfunction and impaired behavior in the context of ischemic stroke." (PMID 34257829, 2021). "Consistent with our findings, recent studies highlight that KAM activates Nrf2, thereby upregulating SLC7A11 and GPX4 to mitigate lipid peroxidation and iron overload in neuronal models of ischemic stroke." (PMID 41533024, 2026). "In the meanwhile, the downstream molecules of NRF2, such as HO-1, SLC7A11, and GPX4, by which Eda-Dex exserts anti-oxidative stress function, have been investigated is ischemic stroke." (PMID 40351418, 2025). "In ischemic stroke models, GPX4 expression is notably downregulated due to several interrelated factors, primarily oxidative stress, depletion of GSH, and disruption of energy metabolism, limiting its protective function." (PMID 40375180, 2025). "To summarize, our data reveal the impact of 15‐PGDH on ischemic stroke, which is achieved by promoting GPX4‐dependent ferroptosis." (PMID 38188604, 2024). "We discover that 15‐PGDH aggravates ischemic stroke in vivo and in vitro, by promoting GPX4‐dependent ferroptosis." (PMID 38188604, 2024). "In this process, the activity of transcription factors CREB and NF‐κB is increased to transcriptionally upregulate the expression of GPX4, thus ablating ischemic stroke‐induced ferroptosis." (PMID 38188604, 2024). "It has been shown that the expression level of GPX4 was significantly reduced during the acute phase of ischemic stroke and that increasing GPX4 levels can protect neurons from ferroptosis." (PMID 37891735, 2023). "This indicates that SLC7A11/GSH/GPX4 was probably one of the targets for DL-NBP to cure ischemic stroke." (PMID 36909944, 2023). "Electroacupuncture, a common treatment in the clinic to improve the neurological function and quality of life of ischemic stroke patients, can suppress neuronal ferroptosis by accelerating the expression of GPX4 and ferritin heavy chain 1 (FTH1) in MCAO rats." (PMID 38026442, 2023). "During ischemic stroke, excessive and lethal accumulation of lipid reactive oxygen species (ROS) in biofilms leads to glutathione depletion and inactivation of GPX4." (PMID 36967397, 2023). "After ischemic stroke, Se supplementation can effectively inhibit GPX4-dependent ferroptosis and endoplasmic reticulum (ER) stress-induced cell death and improve NVU function by promoting GPX4 expression." (PMID 36425577, 2022). "In an animal model of ischemic stroke, peptides containing selenocysteine inhibit ferroptosis by driving GPX4 expression, thus exerting a protective effect on neurons and reducing ischemic core." (PMID 34055196, 2021). "Carvacrol has been found to reduce lipid peroxidation levels and increase GPX4 expression, which help suppress ferroptosis and protect the structure and function of hippocampal neurons in an ischemic stroke gerbil model." (PMID 34257829, 2021). "Pharmacological Se supplementation protects cells from ferroptosis in ischemic stroke via increasing GPX4 expression." (PMID 33132849, 2020). "In a gerbil cerebral ischemia model, carvacrol also successfully protects hippocampal neurons against ferroptotic cell death by increasing the expression of Gpx4, which provides a promising target for ischemic stroke therapies." (PMID 33132849, 2020). "Carvacrol protects against ischemic stroke by inhibiting ferroptosis through increasing the expression of Gpx4." (PMID 33132849, 2020).